AXL (AXL receptor tyrosine kinase)
Diseases named in the same sentence as AXL in open-access papers (continued):
Sharing a sentence is not in itself a finding about the gene and the disease.
colorectal cancer (continued). "Moreover, 36 colorectal cancer tissues and their adjacent normal tissues were obtained to determine the mRNA content of AXL and HIF‐1A." (PMID 32061057, 2020). "In other cancer types, AXL has been implicated in resistance to doxorubicin and cytosine arabinoside in AML, to cisplatin resistance in esophageal cancer, to multiple chemotherapies in NSCLC, and to 5-FU treatment in colorectal cancer." (PMID 32148495, 2020). "Additionally, MZF1 binds to the AXL promoter in cervical and colorectal cancer cell lines and enhances transcription of AXL." (PMID 32148495, 2020). "We studied AXL as new therapeutic target in colorectal cancer (CRC)." (PMID 25966280, 2015). "Point mutations in AXL have not been specifically described in the literature for colorectal cancer, and lower mutation frequencies (3.5%) were reported for primary colorectal cancers in the TCGA database." (PMID 25193853, 2014). "In addition, monoclonal antibodies and small-molecule tyrosine kinase inhibitors specifically targeting AXL are currently in development and their use in colorectal cancer patients should also be further explored." (PMID 25193853, 2014). "Consistent with the role of AXL in promoting EMT in cancer, targeting AXL by selective inhibitors, germline knockout, RNAi, and inactivating mAbs prevented etastasis of various epithelial tumours, including but not limited to, breast, lung, ovarian, and colorectal cancers." (PMID 34638349, 2021). "Using both male and female colorectal cancer samples, Yang demonstrated that XIST is the competitive endogenous RNA of miR93-5p to promote HIF-1 A and then the upregulated AXL level facilitates migration and proliferation of colorectal cancer." (PMID 39639337, 2024). "In patients with colorectal cancer who received anti-EGFR treatments, those with high AXL expression show lower PFS rates than those with low AXL." (PMID 37328828, 2023). "It was found that the biomarkers of efferocytosis (AXL, CD36, UCP2) and macrophage repair indicators SPMs (RvD1, RvE1, LipoxinA4) were significantly increased in animal models and postoperative colorectal cancer patients." (PMID 36691021, 2023). "CD133 and AXL have been described as cancer stem cell markers, and c-MYC as a key regulatory cellular mechanism in colorectal cancer (CRC)." (PMID 33759958, 2021). "XIST is the competitive endogenous RNA of miR‐93‐5p to promote HIF‐1A, and then the upregulated AXL level facilitates the EMT process, migration, and proliferation of colorectal cancer." (PMID 32061057, 2020). "AXL, a receptor tyrosine kinase and an important member of the TAM family (Tyro3, Axl, Mer), is abnormally overexpressed in various malignant tumors, including EC, GC, OC, and colorectal cancer (CRC)." (PMID 40157901, 2025). "As a competitive sponge for miR-93-5p, XIST may act as a positive regulator of HIF-1A, which in turn increased expression of AXL, and thus promoted the EMT process, as well as migration and proliferation in colorectal cancer." (PMID 39830506, 2024). "miR-93-5p could regulate HIF-1A/AXL signaling pathways to facilitate the progression and EMT of colorectal cancer." (PMID 34790052, 2021). "In early colorectal cancer (CRC), AXL was found to be a biomarker of poor prognosis." (PMID 34838035, 2021). "AXL dimerizes with epidermal growth factor receptor (EGFR), which has been shown to regulate FOXM1 expression via an EGFR/RAS/FOXM1/β-catenin axis in colorectal cancer." (PMID 32976773, 2020). "However, depletion of AXL by RNA interference only partially inhibits MZF1-induced migration and invasion of colorectal cancer cells, suggesting that additional MZF1-regulated genes are involved in this process." (PMID 31963147, 2020). "Furthermore, cabozantinib decreases MET, AXL, and AKT phosphorylation in colorectal cancer patient-derived tumor xenografts." (PMID 32055714, 2020).
colorectal cancer (continued). "As a highly potent and highly selective oral inhibitor of FLT3/AXL, gilteritinib showed activity against FLT3D835 and FLT3‐ITD mutations in pre‐clinical testing, although its role on colorectal cancer (CRC) cells is not yet fully elucidated." (PMID 31881122, 2020). "Here we show that AXL, but not MERTK or TYRO3 expression is enhanced in late stage colorectal cancer (CRC) and AXL expression associates with a cell migration gene signature." (PMID 28727830, 2017). "We also found that cell lines express on average 11 druggable mutations, including frequent mutations (>20%) in the receptor tyrosine kinases AXL and EPHA2, which have not been previously considered as potential targets for colorectal cancer." (PMID 25193853, 2014).
triple-negative breast carcinoma (33 papers, 2014 to 2026). An invasive breast carcinoma which is negative for expression of estrogen receptor (ER), progesterone receptor (PR), and human epidermal growth factor receptor 2 (HER2). "AXL, a receptor tyrosine kinase, has emerged as a promising therapeutic target in triple-negative breast cancer (TNBC) due to its critical roles in tumor progression, metastasis, and immune evasion." (PMID 41009462, 2025). "Previous work by Wang and colleagues already demonstrated the potential of 64Cu-labeled anti-human AXL antibodies to visualize AXL+ tumors and monitor the effect of anti-AXL therapies in triple negative breast cancer (TNBC)-bearing nude mice." (PMID 38773967, 2024). "AXL-directed CAR-T cells have proven to be effective at inhibiting the growth of triple-negative breast cancer and chronic myelogenous leukemia." (PMID 37475048, 2023). "A recent report also suggested that AXL expression was regulated by serine/threonine protein kinase PKCα in triple-negative breast cancer." (PMID 36835239, 2023). "In triple-negative breast cancer (TNBC) where AXL is overexpressed, engineered T cells with AXL-CAR-T were able to induce cytokine release and an antigen-specific cytotoxicity." (PMID 35158733, 2022). "In this study, the AXL expression of triple-negative breast cancer cells MDA-MB-231, MDA-MB-436, MDA-MB-453, and MDA-MB-468 were detected by flow cytometry." (PMID 31998790, 2020). "The MDA-MB-231 triple-negative breast cancer cell line was chosen for this study because it is well demonstrated that AXL overexpression in this cell line confers aggressive cell behaviors." (PMID 27829217, 2016). "miR-34a was also described to be involved in the negative regulation of the receptor tyrosine kinase AXL expression and of Akt activation in triple receptor negative breast cancer cells (MDA-MB-231)." (PMID 24587182, 2014). "The miR-34a/AXL interaction was functionally characterized through ectopic overexpression experiments with a miR-34a mimic in two independent triple-negative breast cancer cell lines." (PMID 25337673, 2014). "Similarly, another group experimented with CAR-T cells expressing the IL-7 receptor (C7R) that targets AXL in AXL-positive triple-negative breast cancer (TNBC)." (PMID 38201467, 2023). "Moreover, a study reported that AXL-CAR-T Cells exerted potent anti-tumor cytotoxicity against AXL-positive triple-negative breast cancer (TNBC)." (PMID 36419058, 2022). "Additionally, an AXL CAR-T molecule has shown in vivo anti-tumor effects against triple negative breast cancer (TNBC) in an MDA-MB-231 xenograph model." (PMID 36551940, 2022). "In addition, a previous study has shown that 20G7-D9, a specific anti-human AXL murine IgG1 monoclonal antibody, impaired tumor growth and metastatic spread of triple negative breast cancer cell lines." (PMID 33791875, 2021). "Consistent with the in vitro data, nuclear localisation of AXL and TYRO3 receptors was reported in cancer tissues, including schwannoma, radioresistant triple-negative breast cancer (AXL), CRC, and leiomyosarcoma (TYRO3)." (PMID 40044635, 2025). "For instance, engineered T cells expressing AXL-CAR-T were able to trigger cytokine release and antigen-specific cytotoxicity in triple-negative breast cancer (TNBC), where AXL is overexpressed." (PMID 38391974, 2024). "We previously performed tyrosine phosphoproteome profiling of a panel of triple negative breast cancer (TNBC) and discovered that AXL is hyperphosphorylated in highly aggressive TNBC cell lines." (PMID 34439388, 2021). "In this study, the authors show that AXL activation can control focal adhesion dynamics via PEAK1 and that AXL-mediated PEAK1 phosphorylation is required for metastasis of triple negative breast cancer cells in vivo." (PMID 32681075, 2020). "A phase II study of Foretinib (an oral multi-kinase inhibitor of MET, RON, AXL, TIE-2, and VEGF receptors) in patients with triple-negative breast cancer observed a clinical benefit rate of 46 %." (PMID 27894094, 2017).
triple-negative breast carcinoma (continued). "Recently, expression of AXL has been identified as a predictor for lack of response to EGFR–targeted inhibitors in triple-negative breast cancer cells." (PMID 25337673, 2014). "Additionally, several research reported GSEC could promote the malignant process of triple-negative breast cancer and hepatocellular carcinoma via the GSEC/miR-202-5p/AXL axis and the GSEC/miR-101-3p/SNX16/PAPOLG axis, respectively." (PMID 38409243, 2024).
prostate carcinoma (31 papers, 2014 to 2025). A carcinoma that arises from epithelial cells of the prostate gland. "In prostate cancer, AXL operates in conjunction with other dormancy-associated factors to maintain cellular quiescence." (PMID 40715090, 2025). "Beyond its role in HCC, AXL signalling has been implicated in promoting short-term dormancy in prostate cancer cells, thereby prolonging tumour latency before disease recurrence." (PMID 40715090, 2025). "Apart from AXL, survivin is also frequently associated with biologically aggressive prostate carcinoma." (PMID 37960146, 2023). "The RTK AXL (tyrosine-protein kinase receptor UFO) has been heavily implicated in various aspects of tumorigenesis in several cancer types, and is overexpressed in prostate cancer." (PMID 33105713, 2020). "Increased AXL expression was demonstrated to promote migration and invasion of prostate cancer cells in vitro, and is also associated with a higher frequency of distant metastasis after pancreaticoduodenectomy in patients with pancreatic adenocarcinoma." (PMID 25337673, 2014). "Furthermore, in vitro studies suggest that AXL signaling is associated with prostate cancer development and progression." (PMID 28455956, 2017). "The AXL-Gas6 axis is important in myeloma and prostate cancer cell dormancy, and similarly the MER-GAS6 axis promotes dormancy in acute lymphoblastic leukaemia." (PMID 41091336, 2025). "GAS6 has been shown to down-regulate AXL in prostate cancer cells, GAS6 production by aHSCs has previously been described in the context of fibrosis, and its deficiency reduced fibrosis in mice." (PMID 37004869, 2023). "Gas6 promotes the proliferation of AXL-expressing prostate cancer cells by enhancing Akt phosphorylation." (PMID 37265798, 2023). "Both AXL and GAS6 have been implicated in dormancy in the context of bone marrow metastasis of prostate cancer." (PMID 35158733, 2022). "Many studies have reported that AXL is involved in the pathogenesis and biological behaviour of oral squamous cell carcinoma, gallbladder cancer, prostate cancer, and other cancers." (PMID 36203174, 2022). "RNASE4 stimulates prostate cancer cell proliferation, induces tumor angiogenesis, and activates receptor tyrosine kinase AXL as well as AKT and S6K." (PMID 35752711, 2022). "RNase 4 is presented as a biomarker for prostate cancer, inducing AXL activation that promotes AKT/S6K activation and tumor cell proliferation, and its inhibition reduces the growth of xenograft human prostate tumors." (PMID 35752711, 2022). "This analysis revealed a striking positive correlation between the expression of PKCα (PRKCA gene) and mesenchymal markers vimentin, ZEB1, ZEB2, and AXL in prostate cancer cell lines." (PMID 36818489, 2022). "In prostate cancer, AXL was found to be overexpressed in docetaxel-resistant cell lines, and AXL overexpression alone was found sufficient to induce resistance to docetaxel." (PMID 33672595, 2021). "For example, ligand growth arrest-specific 6 protein (GAS6)/AXL interaction with osteoblasts retains bone-metastatic prostate cancer cells in a dormant state." (PMID 34831167, 2021). "The critical role of GAS6-AXL signaling in prostate cancer cell invasion was previously reported using shRNA targeting AXL in Boyden chamber assays under serum-free conditions with GAS6 as a chemoattractant." (PMID 32055714, 2020). "AXL overexpression has also been observed in resistance to cytotoxic chemotherapies, such as docetaxel, in prostate cancer." (PMID 32245042, 2020). "In prostate cancer, microarray analysis and functional assays revealed that AXL is a critical mediator of cell survival via activation of the Akt-NF-κB signaling pathway." (PMID 31694201, 2019). "On the other hand, AXL knockdown induced proliferation of prostate cancer cells in the presence of osteoblasts." (PMID 31694201, 2019).
prostate carcinoma (continued). "To investigate the expression and activation of AXL in docetaxel-resistant prostate cancer, we established two docetaxel-resistant prostate cancer cell lines (PC3-DR and DU145-DR) by culturing PC3 and DU145 cells in docetaxel in a dose-escalation manner." (PMID 28455956, 2017). "Overall, our results identify AXL as an important mediator of docetaxel resistance in prostate cancer." (PMID 28455956, 2017). "Despite many reports on the function of AXL in drug-resistance, the role of AXL overexpression in the treatment of prostate cancer using docetaxel has been poorly discussed." (PMID 28455956, 2017). "In summary, our research showed that the inhibition of AXL has an antitumor effect in models of docetaxel-resistant prostate cancer." (PMID 28455956, 2017). "Taken together, the data suggest that AXL upregulation activates AKT, ERK, or NF-κB signaling to promote resistance to docetaxel treatment in prostate cancer, perhaps in association with the acquisition of EMT." (PMID 28455956, 2017). "Collectively, our findings suggest that targeting AXL is effective in overcoming docetaxel resistance in prostate cancer." (PMID 28455956, 2017). "AXL promotes migration and invasion of prostate cancer cells in vitro and regulates expression of genes involved in EMT." (PMID 26762579, 2016). "Further, it is noteworthy that AXL is reportedly overexpressed in prostate cancer cell lines and human prostate tumors, and its expression is considerably higher in more aggressive androgen-refractory PC3 and DU145 cells compared with the androgen-dependent cell line LNCaP." (PMID 37960146, 2023). "Consequently, the crucial role of AXL in the progression and metastasis of prostate cancer has made it an attractive therapeutic target, as various synthetic inhibitors have been conducted in clinical trials for AXL-targeted therapies." (PMID 37960146, 2023). "Thus, the drastic AXL-diminishing effect of combining lovastatin with AC extract opened a new avenue to future strategic integration with currently available AXL inhibitors for better treatment against aggressive prostate cancers." (PMID 37960146, 2023). "Interestingly, prostate cancer cells express a repertoire of GAS6 receptors (including AXL, MER and TYRO3), a balanced expression of which has been shown to control dormancy (AXL) or proliferation (TYRO3)." (PMID 34831167, 2021). "AXL activation has also been shown to initiate a dormant state in prostate cancer cells." (PMID 33105713, 2020). "AXL phosphorylation and activation by binding of GAS6 has been associated with increased cell proliferation and survival in various tissues and cancer types including prostate cancer, colorectal cancer, gastric cancer, renal carcinoma and osteosarcoma." (PMID 31694201, 2019). "Further work will be necessary to completely elucidate the mechanisms by which AXL might promote resistance in prostate cancer through the induction of EMT." (PMID 28455956, 2017). "Being of therapeutic interest, we investigated whether AXL inhibition is sufficient to reverse the resistance to docetaxel in prostate cancer." (PMID 28455956, 2017). "Recent studies have found high levels of AXL expression in advanced human prostate cancer tissue." (PMID 28455956, 2017). "The study herein is the first to describe a role of AXL in resistance to docetaxel both in vitro and in vivo, and thus, provides a rationale for the development and use of anti-AXL therapeutics for the treatment of docetaxel-resistant prostate cancer." (PMID 28455956, 2017). "We propose that AXL-targeted therapy, in combination with docetaxel, has the potential to improve the response to docetaxel therapy and reduce resistance induced by prolonged docetaxel therapy in prostate cancer." (PMID 28455956, 2017). "We further sought to identify the signaling events downstream of AXL that might promote the acquired resistance to docetaxel in prostate cancer." (PMID 28455956, 2017).